TTBK1 (tau tubulin kinase 1)
Description:
Serine/threonine kinase which is able to phosphorylate TAU on serine, threonine and tyrosine residues. Induces aggregation of TAU.
Synonyms: BDTK; KIAA1855
Tractability: Small molecule: a structure with a bound ligand is known; a high-quality ligand is known; it belongs to a druggable protein family. PROTAC: its protein half-life has been measured; a small molecule that binds it is known.
Target class: Enzyme; Kinase; Protein Kinase; CK1 protein kinase group
Chemical probes: TTBK1-IN-1 (high quality), TTBK1-IN-2
Gene: Protein-coding gene on chromosome 6 (43,243,481 to 43,288,258, forward strand). Ensembl gene ENSG00000146216.
Subcellular location: Cytoplasm
Subcellular location (Human Protein Atlas): Cytosol; Nucleoplasm
Gene Ontology:
Molecular function: protein serine kinase activity; protein serine/threonine kinase activity; protein tyrosine kinase activity; tau protein binding; tau-protein kinase activity; ATP binding; protein kinase activity
Biological process: learning or memory; negative regulation of gene expression; positive regulation of astrocyte activation; positive regulation of gene expression; positive regulation of microglial cell activation; positive regulation of protein polymerization; substantia nigra development
Cellular component: cytoplasm; cytosol; microtubule associated complex; neuronal cell body; perinuclear region of cytoplasm; microtubule cytoskeleton
Genetic constraint (gnomAD): Loss-of-function variants: 34 observed, 92.09 expected, observed/expected ratio (o/e) 0.37, 90% interval 0.28 to 0.49. The upper end of that interval is the gene's LOEUF score, 0.49, which puts it in group 2 of 6, group 1 being the genes least tolerant of losing a copy. Missense variants: 1,539 observed, 1,672.1 expected, observed/expected ratio (o/e) 0.92, 90% interval 0.88 to 0.96. Synonymous variants: 809 observed, 727.5 expected, observed/expected ratio (o/e) 1.11, 90% interval 1.05 to 1.18.
Homologues: Orthologues: chimpanzee TTBK1 (99% identical), macaque TTBK1 (98% identical), dog TTBK1 (92% identical), pig TTBK1 (91% identical), mouse Ttbk1 (89% identical), rat Ttbk1 (89% identical), guinea pig TTBK1 (84% identical), rabbit TTBK1 (71% identical), tropical clawed frog ttbk1 (66% identical), Caenorhabditis elegans ttbk-7 (22% identical), Caenorhabditis elegans W09C3.1 (10% identical), Caenorhabditis elegans kin-35 (10% identical), and 62 more. Paralogues in human: TTBK2 (36% identical), CSNK1D (11% identical), CSNK1E (11% identical), CSNK1G3 (10% identical), CSNK1G1 (10% identical), CSNK1G2 (10% identical), CSNK1A1 (9% identical), CSNK1A1L (8% identical), VRK2 (8% identical), VRK1 (7% identical), CDC7 (5% identical), VRK3 (4% identical).
Diseases named in the same sentence as TTBK1 in open-access papers:
TTBK1 is named in the same sentence as 25 diseases in open-access papers, as found by Europe PMC text mining. Sharing a sentence is not in itself a finding about the gene and the disease. The quoted sentences say what the papers report.
Alzheimer disease (19 papers, 2014 to 2025). A progressive, neurodegenerative disease characterized by loss of function and death of nerve cells in several areas of the brain leading to loss of cognitive function such as memory and language. "TTBK1 has been implicated in the phosphorylation and aggregation of tau in Alzheimer’s disease (AD)." (PMID 39065802, 2024). "TTBK1 phosphorylation activity is linked to several neurodegenerative diseases like Alzheimer's disease." (PMID 33510822, 2021). "TTBK1 is also known to be associated with Alzheimer’s disease while MYO16 has been found to be associated with pulse pressure." (PMID 29713383, 2018). "Human TTBK kinases have been associated with neurodegeneration, where TTBK1 is thought to phosphorylate Tau protein and promote the progression of Alzheimer's disease and TTBK2 has been linked to another Tau‐related disease, spinocerebellar ataxia 11 (SCA11)." (PMID 28560849, 2017). "Single nucleotide polymorphisms (SNPs) in TTBK1 are associated with decreased Alzheimer's disease risk in studies of Spanish and Han Chinese populations." (PMID 25473830, 2014). "Variants in the gene coding for TTBK1 are associated with Alzheimer's disease, while mutation in TTBK2 causes spinocerebellar ataxia 11 (SCA11), both of which are characterized by pathologic alterations of tau." (PMID 25473830, 2014). "Furthermore, TTBK1 is known to act on neuropathic proteins like tau at pathogenically relevant sites and is overexpressed in Alzheimer’s disease (AD) with single nucleotide polymorphisms associated with late-onset AD." (PMID 38523660, 2024). "Single-nucleotide polymorphisms (SNPs) in TTBK1 are associated with a decreased risk of Alzheimer’s disease in a Han Chinese population, and may contribute to decreased neurofibrillary tangle formation and tau phosphorylation." (PMID 33228809, 2020). "The kinase TTBK1 is predominantly expressed in the central nervous system and has been implicated in neurodegenerative diseases including Alzheimer’s disease, frontotemporal lobar degeneration, and amyotrophic lateral sclerosis through its ability to phosphorylate the proteins tau and TDP-43." (PMID 33228809, 2020). "TTBK1 protein expression is significantly elevated in Alzheimer’s disease (AD) brains, and genetic variations of the TTBK1 gene are associated with late-onset Alzheimer’s disease in two cohorts of Chinese and Spanish populations." (PMID 24808823, 2014). "Tau tubulin kinase-1 (TTBK1), a neuron-specific tau kinase, is highly expressed in the entorhinal cortex and hippocampal regions, where early tau pathology evolves in Alzheimer’s disease (AD)." (PMID 37853497, 2023). "While efforts have been devoted to characterizing the impact of TTBK1 inhibition in diseases like Alzheimer’s disease and amyotrophic lateral sclerosis, TTBK2 inhibition has been less explored." (PMID 37059819, 2023). "TTBK1 is highly expressed in the entorhinal cortex and the perforant path region, two specific brain regions involved in the early stage of Alzheimer’s disease pathology, and thus, has a critical role in axonal degeneration." (PMID 34889895, 2021). "TTBK1 has been shown to co-localize with diffuse phospho-Ser422 tau in pre-tangle Alzheimer's disease neurons, and increased levels of TTBK1 have been observed in AD frontal cortex and enhance the toxicity of tau in a P301L mouse model." (PMID 25473830, 2014). "Ttbk1b (orthologous to human TTBK1), a neuron-specific tubulin kinase 1b, involves in pathological phosphorylation of tau and TDP-43 and drives neurodegeneration (e.g., Alzheimer’s disease and other tauopathies)." (PMID 39083243, 2025). "Both TTBK1 and TTBK2 were initially identified as tau kinases and TTBK1 has been shown to phosphorylate tau epitopes commonly observed in Alzheimer’s disease and other tauopathies." (PMID 29409526, 2018).
Alzheimer disease (continued). "TTBK1 and TTBK2 were originally purified on the basis of their kinase activity on the microtubule binding protein tau at several pathological phospho-tau epitopes known to accumulate in Alzheimer's disease." (PMID 25473830, 2014).
tauopathies (7 papers, 2014 to 2025). "The restriction of TTBK1 expression to the CNS and its ability to phosphorylate tau at S422, a phosphorylation site previously shown to be increased in a variety of neurodegenerative diseases, makes TTBK1 an exciting target for the treatment of tauopathies." (PMID 32255788, 2020). "Previous work using phospho-peptide mapping indicates that TTBK1 can phosphorylate tau at serine residues 198, 199, 202, 422 and at tyrosine 197; all sites enriched in paired helical filaments which characterize tauopathies." (PMID 32255788, 2020). "Therefore, the cumulative evidence linking TTBK1 to disease and the restriction of TTBK1 expression to the CNS makes TTBK1 an interesting target for the treatment of tauopathies." (PMID 32255788, 2020). "Therefore, we believe that due to the CNS restricted expression of TTBK1, pharmacological inhibition of this kinase represents a promising therapeutic approach in the treatment of tauopathies." (PMID 32255788, 2020). "To test whether TTBK1 driven phosphorylation of tau influences tauopathy phenotypes, we crossed our hTTBK1-cat Tg line with C. elegans strains expressing either low or high levels of wild-type human tau (isoform 1N4R)." (PMID 29409526, 2018). "This suggests that TTBK1 is significantly involved in progression of tauopathy." (PMID 24808823, 2014). "Thus, TTBK1 is a novel therapeutic target of neuroinflammation-associated neurodegeneration, such as AD, FTD, and tauopathy-related ALS complex." (PMID 24808823, 2014). "Research has indicated that tau tubulin kinases TTBK1 and TTBK2, which are upregulated in tauopathies, have been shown to mediate the pathological phosphorylation of both tau and TDP-43, suggesting they act as molecular links converging on both proteins." (PMID 40722308, 2025). "The identification of TTBK1 and TTBK2 as both tau and TDP-43 kinases indicates a possible shared mechanism for the initiation of TDP-43 proteinopathy and tauopathy in FTLD." (PMID 29409526, 2018). "No specific small molecule inhibitors targeting TTBK1 or TTBK2 has been reported to date, despite their potential roles contributing to tauopathies by hyperphosphorylating tau." (PMID 25473830, 2014).
frontotemporal lobar degeneration (4 papers, 2020 to 2025). "In human tissue from patients with frontotemporal lobar degeneration (FTLD-TDP) or amyotrophic lateral sclerosis (ALS), TTBK1 is increased and co-localizes with TDP-43-positive inclusions." (PMID 33228809, 2020).
proteinopathies (4 papers, 2014 to 2025). "In mammalian cell culture and C. elegans models, the kinase domains of TTBK1 and TTBK2 phosphorylate Ser409 and Ser410 on TDP-43, epitopes consistently associated with TDP-43 proteinopathies including ALS and FTLD-TDP." (PMID 33228809, 2020). "TTBK1 phosphorylates both TDP-43 and tau and has been implicated in proteinopathies that feature these inclusions, including FTLD and ALS." (PMID 33228809, 2020). "Taken together these data support a pivotal role for TTBK1/2 hyperactivity in TDP-43 proteinopathy." (PMID 25473830, 2014). "TTBK1/2 may be attractive drug targets for therapeutic interventions in TDP-43 proteinopathies such as FTLD-TDP and ALS." (PMID 25473830, 2014). "Finally, to explore whether TDP-43 kinase hyperactivity could underlie the etiology of TDP-43 proteinopathies, we immunostained tissue from FTLD-TDP and ALS for TTBK1/2." (PMID 25473830, 2014). "It remains unknown whether changes in TTBK1 and TTBK2 activity, abundance, and proteolytic processing influence tau- and TDP-43-proteinopathies." (PMID 29409526, 2018).
cognitive deficits (3 papers, 2020 to 2025). "Studies using murine models demonstrate that TTBK1 overexpression and increased tau phosphorylation contribute to cognitive impairment." (PMID 41009668, 2025). "Future experiments will be needed to determine whether chronic inhibition of TTBK1, presumably over the course of several months, would ameliorate the cognitive deficits demonstrated in tau transgenic models of disease." (PMID 32255788, 2020). "Moreover, TTBK1 might be involved in the initial stages of tau phosphorylation and pre-tangle formation in cognitive disorders pathology." (PMID 38536493, 2024).
Insulin resistance (2 papers, 2022 to 2024). Increased resistance towards insulin, that is, diminished effectiveness of insulin in reducing blood glucose levels. "The present study provides evidence supporting the idea that hyperinsulinemic condition causes neuronal insulin resistance, as indicated by the downregulation of insulin signalling molecules, including PI3K/AKT, with the upregulation of GSK-3β and TTBK1." (PMID 38536493, 2024).
spinocerebellar ataxia (2 papers, 2020 to 2023). "Since loss-of- function mutation of Ttbk2 leads to spinocerebellar ataxia 11 and neuron-specific deletion of Ttbk2 induces loss of Purkinje cells, development of TTBK1-specific inhibitor such as ASO-Ttbk1, is necessary to avoid unwanted off-target effect." (PMID 37853497, 2023). "These mice may be a model for studying the role of TTBK1 in neuronal health and disease, and may indicate a previously unknown role for TTBK1 in cerebellar disorders such as spinocerebellar ataxia." (PMID 33228809, 2020). "In addition to providing a system to study the neuronal functions of TTBK1, iTTBK1 mice may represent a new model for spinocerebellar ataxia or other disorders characterized by cerebellar dysfunction and degeneration." (PMID 33228809, 2020).
spinocerebellar ataxia type 11 (2 papers, 2023). Spinocerebellar ataxia type 11 (SCA11) is a subtype of autosomal dominant cerebellar ataxia type III (ADCA type III) characterized by the early-onset of cerebellar signs, eye movement abnormalities and pyramidal signs. "Recently reported TTBK1 inhibitors target not only TTBK1 but also TTBK2, which loss of function mutation is known to lead to spinocerebellar ataxia 11 due to the similarity of catalytic domains between these two tau-kinases." (PMID 37853497, 2023).
diabetes (1 paper, 2024). "The current study aimed to investigate the potential contribution of liraglutide and pramlintide in the prevention of diabetes-induced cognitive dysfunction and their effect on the PI3K/AKT/GSK-3β/TTBK1 pathway in type 2 diabetic (T2D) rat model." (PMID 38536493, 2024).
glaucoma (1 paper, 2025). Increased pressure in the eyeball due to obstruction of the outflow of aqueous humor. "The overexpression of TTBK1 in ocular samples from POAG patients indicates a potential involvement of this gene in neurodegenerative pathways that are common to both glaucoma and AD." (PMID 41009668, 2025). "Furthermore, the identification of DEGs, such as TTBK1 and CTGF/CCN2, which are implicated in neurodegenerative pathways, supports the biological overlap between glaucoma and diseases like Alzheimer’s." (PMID 41009668, 2025).
ischemic stroke (1 paper, 2022). A stroke disorder caused by obstruction of blood flow to the brain, due to thrombotic (local blood clot formation) or embolic (due to a blood clot or other material traveling from another site) event. "The effect of TTBK1 methylation on ischemic stroke was inconsistent between samples from stage one and stage two." (PMID 35345488, 2022). "Indeed, the associations between the methylation levels of TTBK1, TBX2_1 and C17orf82_2 and ischemic stroke were not significant at target level." (PMID 35345488, 2022).
neurodegenerative disease (8 papers, 2014 to 2024). A disorder of the central nervous system characterized by gradual and progressive loss of neural tissue and neurologic function. "Mounting evidence has shown that neurons that undergo die back neurons seen in neurodegenerative diseases possess microtubule-associated molecules in the cell soma such as TTBK1 or pCRMP2 as well as phosphorylated tau protein." (PMID 32019603, 2020). "Accumulating evidence has linked the expression or activity of the tau kinase TTBK1 with neurodegenerative diseases." (PMID 32255788, 2020). "In addition to PDE2A, another protein that was increased at 3 and 24 weeks post injury was tau tubulin kinase 1 (TTBK1), which is known to be linked to the development of several neurodegenerative diseases such as ALS, FTLD, and AD." (PMID 35850691, 2022). "We demonstrate substantial lowering of tau phosphorylation at multiple sites implicated in disease, suggesting that TTBK1 inhibitors may represent an exciting new approach in the search for neurodegenerative disease therapies." (PMID 32255788, 2020). "Another tau tubulin kinase, TTBK1, has also been implicated in neurodegenerative disease." (PMID 33228809, 2020). "TTBK1/2 have described functions in the brain and have become sought after targets for neurodegenerative disease therapies." (PMID 37059819, 2023). "Therefore, the design of new TTBK1 inhibitors is an emerging area of research to tackle neurodegenerative diseases, including AD." (PMID 39065802, 2024). "Both TTBK1 and TTBK2 have been previously implicated in neurodegenerative diseases." (PMID 25473830, 2014). "Like TTBK1/2, PAK, MARK, and TAOK family kinases have implications in neurodegenerative disease signaling." (PMID 37059819, 2023).
cancer (4 papers, 2015 to 2022). A tumor composed of atypical neoplastic, often pleomorphic cells that invade other tissues. "Eight understudied kinases were found to have hotspot mutations in at least one cancer (CDC42BPA, DYRK1B, DYRK4, LMTK3, MAPK15, NEK7, TSSK1B, and TTBK1), with DYRK4, LMTK3, MAPK15, and NEK7 all having significant hotspot mutations in STAD." (PMID 33205077, 2020). "Likewise, none of the Epi‐LumB specific markers, i.e. ZNF132, TTBK1 and KCNA3 have been described as tumor suppressors and it is not clear at this point whether epigenetic inactivation of these genes represent driver events that contribute to cancer development." (PMID 25468711, 2015).
brain disease (1 paper, 2016). "Two other, closely related +TIPs firmly implicated in brain disease are tau-tubulin kinase 1 and 2 (TTBK1 and TTBK2)." (PMID 26969328, 2016).
neurological disorders (1 paper, 2024). "Further studies supported that the kinase TTBK1 had been associated with neurological disorders and is primarily expressed in the central nervous system." (PMID 38536493, 2024).
TTBK1 also shares sentences with these, for which no sentence is quoted: amyotrophic lateral sclerosis (3 papers); cerebellar disorder (1); cognitive disorder (1); Corticobasal Degeneration (1); Down syndrome (1); lymphoma (1); Onset (1); Pick disease (1); progressive supranuclear palsy (1); tumor (1).